IL5 (interleukin 5)
Diseases named in the same sentence as IL5 in open-access papers (continued):
Sharing a sentence is not in itself a finding about the gene and the disease.
asthma (continued). "Therefore, we aimed to investigate the risk of CV events of anti-IgE and anti-IL5/IL5R therapies in adult patients with severe asthma by using data on a nationwide scale from 2017 to 2021." (PMID 40823190, 2025). "In addition, stress has a stimulating effect on the production of certain cytokines (e.g., interleukin (IL)‐4, IL‐5, IL‐13) associated with asthma." (PMID 40702946, 2025). "IL‐5 is a potent pro‐inflammatory cytokine that regulates the maturation, proliferation, activation, and migration of eosinophils in asthma, which are critically implicated in asthma severity." (PMID 41159221, 2025). "We did not directly compare HDM exposure between our mixed background mice and C57BL/6 mice, which are generally more prone to neutrophilic inflammation in ovalbumin-induced asthma models, which may underlie the weaker IL-4, IL-5 and IL-13 responses observed." (PMID 41146597, 2025). "The eosinophilic inflammation associated with asthma is orchestrated by IL-5." (PMID 40136649, 2025). "Moreover, asthma is associated with the occurrence of atopic dermatitis, chronic sinusitis, allergic rhinitis, and a high profile of T2-type cytokines, such as IL-4, IL-5 and IL-13." (PMID 40723867, 2025). "Type 2 (T2)-high asthma, characterized by eosinophilic inflammation and elevated IL-4, IL-5, and IL-13 pathways, has been associated with a more robust Th2 response, which may mitigate the hyperinflammatory state triggered by SARS-CoV-2 infection." (PMID 41149067, 2025). "Released following airway epithelial injury, it activates the ST2 receptor, induces the production of IL-4, IL-5, and IL-13 by Th2 cells, mast cells, and other cell types, drives eosinophilic inflammation and airway hyperresponsiveness, and is closely linked to asthma susceptibility." (PMID 41561024, 2025). "In the PPI network analysis, lililin was found to be associated with three asthma drug targets (IgE, IL-5, and IL-4), further indicating that lililin may be a potential therapeutic target for asthma." (PMID 39806440, 2025). "Furthermore, different studies have shown that Mg2+ can interfere with the activation of NF-κB, a central pathway in the transcription of proinflammatory genes, such as TNF-α, IL-4, IL-5, and IL-13, all of which are implicated in asthma pathophysiology." (PMID 40868515, 2025). "Asthma often begins in childhood (childhood-onset asthma) and is often associated with exaggerated type 2 immunity, involving the production of the prototypical type 2 cytokines IL-4, IL-5, and IL-13." (PMID 41145900, 2025). "In asthma-susceptible neonatal BALB/c mice, RvE2 reduced eosinophil counts and IL-4, IL-5 and IL-13 levels, suggesting that RvE2 may prevent asthma risk." (PMID 39720728, 2024). "In asthma patients, elevated levels of airway and blood eosinophils as well as IL-5 have been demonstrated in multiple studies and are considered to be a hallmark of certain asthma phenotypes, particularly those unresponsive or refractory to ICS, making them appealing therapeutic targets." (PMID 39518477, 2024). "In addition, asthma conditions have been linked to increased levels of inflammatory cytokines such as IL-4, IL-5, IL-17, IL-13, and TNF-α in addition to decreased IFN-γ and IL-10." (PMID 39295946, 2024). "The level of IL-5 in the sputum of obese asthmatics was significantly higher than that of leaner asthmatics, suggesting that the amount of IL-5 cytokines is associated with obese asthma." (PMID 38365763, 2024). "However, pre-biologic BEC and FeNO were strongly associated with lung function improvement for both anti-IgE and anti-IL5/5R therapies, with BEC also associated with improved asthma control for patients treated with anti-IL5/5R therapies." (PMID 38711495, 2024). "Asthma, characterized by chronic airway inflammation, shares underlying immunological mechanisms with CRSwNP, such as Type 2 inflammatory responses involving cytokines like IL-4, IL-5, and IL-13." (PMID 39328679, 2024).
asthma (continued). "IL-4, together with IL-5 and IL-13, are Type 2 (T2)-high asthma-associated cytokines that are assumed to provide the main asthma manifestations, such as bronchial hyperreactivity, mucus hyperproduction, immunoglobulin E (IgE) synthesis, and airway eosinophilia." (PMID 39767651, 2024). "These SNPs may influence IL-5 signaling pathways, affecting the regulation of the inflammatory response in asthma and other diseases associated with eosinophilia, since IL-5 plays a fundamental role in the maturation and differentiation of eosinophils." (PMID 39125709, 2024). "Murine lung-resident ILC2s produce IL-5 in response to influenza infection, resulting in increased eosinophil recruitment, which may cause asthma exacerbation." (PMID 38684766, 2024). "Perhaps complicating this result with respect to obesity, another study of 131 subjects with severe asthma found that while BMI positively associated with sputum IL-5 (eosinophil growth factor) and bronchial submucosal eosinophil counts, it did not correlate with sputum or blood eosinophil counts." (PMID 39200943, 2024). "The novel interleukin-5-targeting biologics, for instance, can significantly reduce circulating blood eosinophils, which is associated with fewer asthma exacerbations and improved asthma management." (PMID 37731511, 2023). "The role of eosinophilic airway inflammation, a classic feature of asthma predominantly driven by IL-5 and IL-13, in bronchiectasis is unclear, but association with disruption of the airway epithelium through eosinophil degranulation and increased mucus production is plausible." (PMID 37780108, 2023). "However, the evidence is limited by sample size and far than conclusive and suggest the need of future studies to evaluate the risk of infections in patients with asthma receiving anti-IL-5 treatments." (PMID 38268596, 2023). "Although IL-5+ and IL-13+ Tc cell levels were increased in all patient groups compared to HCs, IL-9+ Tc cell frequencies were specifically associated with uncontrolled asthma." (PMID 37612281, 2023). "T2-high asthma phenotype as compared to T2-low phenotype is associated with higher blood eosinophil count, a greater expression of IL-5 in airway mucosa, more severe airway hyper-responsiveness, larger total serum IgE, and higher fractional exhaled nitric oxide (FeNO)." (PMID 37108417, 2023). "The discovery of the mechanism underlying allergic disease, mouse models of asthma, and bronchoscopy studies provided initial insights into the role of Th2-type cytokines, including interlukin (IL)-4, IL-5 and IL-13, which became the target of monoclonal antibody therapy." (PMID 37259416, 2023). "They confirmed that tissue IL-5 was the main positive determinant of eosinophilic inflammation and that IL-5 positive nasal polyps were associated with a higher likelihood of suffering from comorbid asthma." (PMID 36832203, 2023). "In fact, the level of Th1 cytokines IL-12 and IFN-ɣ as well level of Treg cytokine IL-10 in lung of asthma mice was lower than control, and inversely, Th2 cells response-associated the cytokines IL-4, IL-5, and IL-13 had a significant increase in lung of asthma mice compared to the control group." (PMID 36685604, 2022). "Asthma and AD are frequently associated with atopy and are characterized by elevated levels of type 2 cytokines (IL-4, IL-5, IL-13), which cause IgE production, mast cell activation, and basophil and eosinophil recruitment, well-known cellular actors in IgE-mediated inflammatory response." (PMID 36364420, 2022). "The effects of IL-5 or IL-5 inhibition on mast cell antiviral responses may be important in virus-associated exacerbation of asthma." (PMID 35313976, 2022). "Finally, elevated local polyclonal IgE is correlated with increased ECP, IL-5, tissue eosinophilia, and the presence of SE-specific IgE, which are also associated with asthma comorbidity and recurrence after surgery." (PMID 36159836, 2022).
asthma (continued). "IL-4, IL-5, and IL-13 are type 2 cytokines associated with asthma." (PMID 35111694, 2021). "Particularly, type 2 (T2)-high asthma is a complex endotype associated with high type 2 inflammatory markers including immunoglobulin E (IgE), interleukins (IL)-4, IL-5, and IL-13, and it is characterized by AHR, eosinophilia, and excessive airway mucus production." (PMID 34572466, 2021). "Interleukin-5 (IL-5) is a lineage-specific cytokine that increases eosinopoiesis and plays an important role in diseases that are associated with greater levels of eosinophils, such as asthma." (PMID 34960631, 2021). "Similarly, the lead variant at the IL5/IL13 locus linked with a decreased risk of asthma was associated with an increased risk of psoriasis." (PMID 34103634, 2021). "Therapy against IL-5 hampers eosinophil maturation, activation, and survival, whereas the corticosteroid therapy causes eosinophil apoptosis, favoring the switch to a more neutrophilic phenotype of asthma when administered at the highest dose." (PMID 32674292, 2020). "This study aimed to identify the correlation between serum levels of ghrelin, obesity, and asthma with the possible role of some associated inflammatory cytokines—particularly IL-4, IL-5 and IL-21—in children to investigate ghrelin as a future target in the management of asthma." (PMID 32143340, 2020). "Indeed, ILC2s are producers of type 2 cytokines such as IL-5 and IL-13 at sites of inflammation and have been implicated in the pathogenesis of several inflammatory diseases, including asthma." (PMID 32582171, 2020). "Moreover, treating asthma patients with ICS has been shown to suppress the transcription of the gene encoding IL-5." (PMID 32467785, 2020). "miR146a-inhibitor attenuated OVA-induced allergic asthma by increasing Th1 cytokines in OVA-induced allergic asthma model, and the treatment of miR146a-inhibitor can reduce the inflammation caused by asthma, followed by the down-regulation of IL-5 and IL-13 in sorted ILC2." (PMID 32600285, 2020). "Asthmatics experimentally infected with rhinovirus had increased viral titres compared to infected healthy controls, with greater airway inflammation, bronchial hyperreactivity, and reductions in lung function associated with increased levels of IL-4, IL-5 and IL-13 in BAL." (PMID 30764493, 2019). "Moreover, IL-5 has been implicated in enhanced eosinophilic accumulation, activation, and survival as well as aggravated bronchial inflammation and asthma symptoms." (PMID 31861989, 2019). "As a classic feature of asthma, IL5 activates eosinophils and cause airway inflammation." (PMID 31780733, 2019). "Indeed, in murine models of asthma, it has been shown that IL-5 gene deletion was associated with a parallel suppression of both lung eosinophilia and bronchial remodeling." (PMID 31920718, 2019). "Like asthma, blood eosinophilia is often mild (if present) in these disorders, and pathogenic mechanisms likely include allergic sensitization, and numerous cell types and mediators beyond eosinophils and IL-5." (PMID 29682504, 2018). "As IL‐18 stimulates T cells to produce increased IFN‐γ, IL‐13 and IL‐5 23, and IL‐13 and IL‐5 are potent Th2 cytokines, which play key pro‐inflammatory role in atopic asthma, it is believed that IL‐18 ought to be a causative factor for asthma." (PMID 28922563, 2018). "Group II ILCs specifically, secrete the cytokines IL-5, IL-13, IL-9, amphiregulin, and low quantities of IL-4 and have been linked to several lung-associated conditions including pathogen infections (viruses and helminths), asthma, and pulmonary fibrosis." (PMID 30413212, 2018). "A respiratory allergy such as asthma is predominantly caused by Th2 inflammatory responses in the airway, which are characterized by the induction of Th2 cytokines including IL-4, IL-5, and IL-13 that lead to IgE production, increased mucus production, and eosinophilia." (PMID 28824649, 2017).
asthma (continued). "The most important characteristic feature of asthma is chronic airway inflammation which is associated with increased number of Th2lymphocytes and their cytokines (IL-4, IL-5, IL-9, and IL-13) while Th1 lymphocytes and their cytokines (IL-2, IFN-γ, and IL-12) are reduced." (PMID 28824424, 2017). "Therefore, excessive cytokines IL-4, IL-5, and IL-13 produced by Th2 cells are significant risk factors in asthma pathogenesis." (PMID 27870920, 2016). "A study looking at adults also showed that atopy and asthma were also associated with the production Th2 cytokines, including IL-5 in response to TT stimulation, suggesting that in individuals biased towards IL-5 production to TT corresponds with strong responses to the vaccine." (PMID 27926921, 2016). "The IL-5-producing Th2 cells have a pathogenic role in human asthma." (PMID 25852682, 2015). "The suppressive effects of ME on PGE2 formation may contribute to its increased antiallergic activity, as PGE2 may mediate asthma development and inflammation associated with IL-4 and IL-5, which are produced by helper T cells." (PMID 25960618, 2015). "Different conditions are associated with eosinophilia, such as asthma, atopic diseases, helminth infestation, drug hypersensitivity and malignancies; for these reasons several monoclonal antibodies such as anti-IL5 mepolizumab (Bosatria®), reslizumab and benralizumab have been studied." (PMID 25671117, 2015). "The recruitment of eosinophils in the tissues of IL-5 gene-deficient mice and failed therapeutic trials with humanized anti-IL-5 monoclonal antibodies in asthma and other gastrointestinal disorders, indicate that eosinophils may have different subsets." (PMID 27840774, 2015). "Interestingly, the EPHX1 Y113H and IL5 C-703T genes showed an antagonistic character of gene-gene interactions exclusively in women with both pathogenetic variants of asthma." (PMID 24895604, 2014). "Excessive production of IL-4, IL-5, and IL-13 was implicated in the development of asthma." (PMID 24936861, 2014). "However a clinical application of CpdA-like molecules for the treatment of inflammatory and Th1-mediated autoimmune diseases must be carefully studied taking into account the association of GATA-3 and IL-5 with allergic diseases such as asthma pathogenesis." (PMID 22496903, 2012). "Our data indicate that CF has profound inhibitory effects on airway inflammation in a mouse model of asthma, and these effects were caused by the suppression of Th2 cytokines (IL-5), B cell-dependent production of OVA-specific IgE, and eosinophil CCR3 expression." (PMID 22439901, 2012). "Th2 cells and their signature cytokines IL-4, IL-5, and IL-13 have key pathogenic roles in asthma." (PMID 21772663, 2011). "Frequent asthma attacks in children are associated with elevated IL-5 serum levels (p = 0.013)." (PMID 21179211, 2010). "High IL-5 serum levels are associated with frequent asthma attacks in children." (PMID 21179211, 2010). "Frequent asthma attacks were significantly associated with higher circulating IL-5 levels." (PMID 21179211, 2010). "In addition studies in IL-5 deficient mice as well as in human subjects with asthma treated with anti-IL-5 demonstrate reduced numbers of eosinophils, reduced TGF-β1+ eosinophils, and reduced airway remodeling." (PMID 21040544, 2010). "Our previous results also indicated that vitamin A deficiency (VAD) exacerbated ovalbumin‐induced asthma and lung inflammation by enhancing inflammatory cell infiltration and significantly increased levels of type 2 cytokines, particularly interleukin‐5 (IL‐5) and IL‐13." (PMID 39803223, 2025). "Conversely, eosinophilic asthma, classified as type-2 high asthma, is commonly associated with allergic triggers and is characterized by a significant presence of eosinophils within the airways, and associated with elevated levels of cytokines, like IL-4, IL-5, IL-13, and IgE." (PMID 40512736, 2025).
asthma (continued). "Further studies, particularly using lung tissue samples are necessary to understand whether overweight/obesity is associated with increased IL-5 production but reduced eosinophil recruitment and activation in the lungs, compared to children with normal weight and asthma." (PMID 39902293, 2024). "The discrepancy may be due to the effect of IL-5 on asthma risk through a complex immune cascade." (PMID 39175819, 2024). "Furthermore, TNF-α and IL-6 also have been highlighted to be responsible for the association between obesity and asthma, since they could enhance the production of IL-4 and IL-5, being both found raised in eosinophilic asthma." (PMID 37920579, 2023). "In this research, therefore, we aimed to investigate the effect of IL-3, IL-5, and GM-CSF on the proliferative properties of blood rEOS-like and iEOS-like cells that might be associated with the expression of their receptors in asthma patients." (PMID 36497064, 2022). "However, it is noted that blood eosinophils could be potentially upregulated toward the insufficient level to respond to additional stimulation, particularly IL-5, because these constitutionally predispose to type-2 inflammatory mediators in asthma." (PMID 36291665, 2022). "For example, it is thought an inflammatory type 2 response associated with cytokines (IL-4, IL-5, and IL-13) and the clinical inflammatory phenotype of asthma marked by eosinophilia may have protective effects through the activation of the antiviral host defence and promotion of viral clearance." (PMID 36105903, 2022). "Type 2 inflammation (type 2 T helper cell lymphocyte) is common in asthma patients, and it is linked to certain inflammatory cells (mast cells, eosinophils, type 2 T helper cell lymphocyte, IgE-producing plasma cells, and basophils) and cytokine profiles (IL-13, IL-5, IL-4)." (PMID 34516405, 2021). "These cytokines are important in asthma: IL-13 and IL-4 promote antibody class switching to IgE in B cells, IL-13 can also act on smooth airway muscle cells, causing bronchoconstriction and aiding in the remodeling of airways, and IL-5 stimulates the production of eosinophil." (PMID 34831860, 2021). "The best known phenotype of asthma is allergic asthma, in which these symptoms are caused by inhaled allergens such as house dust mites, animal dander, fungi, and pollens, triggering an immunological response driven by T helper type 2 (Th2) cells and their associated cytokines IL-4, IL-5, and IL-13." (PMID 32194407, 2020). "In conclusion, the plasma levels of CCL5 and IL-5, as well as the eosinophil count in peripheral blood, may not be useful diagnostic biomarkers to evaluate airway inflammation and monitor asthma severity during sandstorms, especially if the patients have used ICS." (PMID 32467785, 2020). "This terminology was expanded to another commonly occurring human asthma phenotype, with justification provided for the introduction of an “allergic equine asthma” phenotype associated with a Th-2 predominant response, characterized by increased expression of IL-4 and IL-5 in BAL-derived cells." (PMID 31694631, 2019). "The fact that IL-5 and IL-5Ra antagonists have been tested targeting not only severe asthma but also other diseases (some of which are associated, e.g., nasal polyposis) could pave the way for the discovery of biomarkers that enable the clinician to chose the right drug for the patient." (PMID 28913336, 2017). "Accordingly, cytokines associated with suppressed function in asthma (IFN-γ and IL-10) which could be secreted by Treg cells increased in the treated compared with the untreated group, whereas cytokines associated with attack and progression of asthma (IL-4 and IL-5) decreased." (PMID 27527926, 2016).